MFN2 (mitofusin 2)
Diseases named in the same sentence as MFN2 in open-access papers (continued):
Sharing a sentence is not in itself a finding about the gene and the disease.
tumor (continued). "All data indicated that circ-MFN2 silencing could restrain the tumor growth of CRC." (PMID 34093664, 2021). "Furthermore, silenced circ-MFN2 also reduced the tumor volume and weight of CRC in vivo." (PMID 34093664, 2021). "In parallel, BAG5 also modulates mitochondrial fission-fusion balance, as evidenced by increased MFN2 and decreased DRP1 expression upon BAG5 silencing, leading to enhanced mitochondrial fusion and reduced tumor aggressiveness." (PMID 40787462, 2025). "Mitofusin-2 (MFN2) knockdown in CD8+ T cells suppresses mitochondrial metabolism and function, thus accelerating tumor growth." (PMID 40122853, 2025). "Among them, TAZ was up-regulated in tumor tissue compared with para-cancerous tissue, and the expression of the remaining eight genes (including SLC25A4, SLC25A5, PARK, PINK1, MFN2, HUWE1, VPS13D, and LRBA) was down-regulated in tumor tissue." (PMID 38373978, 2024). "Accordingly, lower levels of DDR1, MFN2 and OPA1 and higher levels of pAMPK were detected in WM983B and A375M2 tumours, compared to WM983A and A375P tumours as shown in vitro." (PMID 37217519, 2023). "We discovered downregulation of mito-fusion protein OPA1 (mitochondrial dynamin-like 120-kDa protein) and MFN2 (mitofusin-2) and upregulation of mito-fission protein DRP1 (dynamin-related protein 1) in tumor cells with SIRT1 KO." (PMID 37063423, 2023). "Indeed, it is necessary to understand, for instance, the molecular mechanisms through which the induction of MFN2 reduces the OXPHOS metabolism in PDAC since numerous authors have reported that mitochondrial fusion favors an increase in energetic efficiency of both tumor and normal cells." (PMID 35565283, 2022). "Mitofusin-2 (MFN2) profoundly inhibits cell growth and proliferation in a variety of tumor cell lines and rat vascular smooth muscle cells." (PMID 35453623, 2022). "Our study discovered that circ-MFN2 silencing restrained the proliferation, metastasis and radioresistance of CRC cells in vitro and inhibited CRC tumor growth in vivo." (PMID 34093664, 2021). "High expression of Mfn2, enhanced OXPHOS respiratory complex and ATP synthase, which facilitates the proliferation and progression of tumor cells, thus inducing doxorubicin resistance in Jurkat leukemia cells." (PMID 34868997, 2021). "The same study found that the knockdown of mitofusin 2 (MFN2), key for fusing mitochondria, suppressed the respiratory activity of tumor cells." (PMID 34831420, 2021). "In contrast, p-eIF2α was predicted to negatively regulate tumor suppressors like the homeobox protein HOXA10, estrogen-related receptor alpha (ESRRA), polycomb group protein ASXL1, and mitofusin 2 (MFN2) function 43–46." (PMID 34330898, 2021). "Elevated mTORC2 expression in MFN2 knockout MCF-7 and A549 cells appears to play a major role in mediating tumor growth and progression." (PMID 28176801, 2017). "We treated MFN2 knockout MCF-7 and A549 cells, which developed profound tumor with severe invasion, with mTORC1/2 inhibitor P529." (PMID 28176801, 2017). "MFN2 mRNA levels were determined in 115 pairs of human HCC and corresponding non-tumor hepatic tissues." (PMID 27389277, 2016). "L-Mfn1- and L-Mfn2-KO mice showed no significant liver damage or tumor development, although a small percentage of L-Mfn1, Mfn2 double KO mice developed tumors." (PMID 41401035, 2025). "Furthermore, research has demonstrated that overexpression of MFN2 promotes the interaction between the mitochondria and the ER by binding to the ER-resident Ca2+-ATPase SERCA2 in tumor-infiltrating CD8+ T cells." (PMID 40661148, 2025). "Moreover, pS473-TRIM28 downregulates MFN2 (Mitofusin-2), thus reducing the excessive fusion of mitochondria, enabling BC cells to survive in the changes in tumor microenvironment (TME), thus promoting tumor growth." (PMID 39100077, 2024).
tumor (continued). "Through detecting the tumor volume and tumor weight, we found that the absence of circ-MFN2 significantly reduced the tumor volume and tumor weight of CRC, and markedly enhanced the sensitivity of CRC tumors to radiation." (PMID 34093664, 2021). "The molecular processes of mitochondrial dynamics are governed by MFN2 (mitofusin 2), OPA1 (optic atrophy 1), FIS1 (mitochondrial fission 1), and DRP1 (dynamin-related protein 1), which are overexpressed in tumour cells and crucial for the development of the malignant phenotype." (PMID 35008887, 2021). "The first study testing Mfn2 expression in BC pointed out that tumor compared to adjacent non-tumorous tissue was characterized by decreased Mfn2 protein levels and significantly higher Mfn2 mRNA levels." (PMID 34441434, 2021). "The activity of caspase-3 (an apoptosis marker) and the mRNA expression of STING1, MFN1, and MFN2 in tumor extracts was not changed by IKE." (PMID 34195205, 2021). "To further confirm the role of circ-MFN2 in CRC, we constructed CRC tumor xenograft models." (PMID 34093664, 2021). "Previous research has shown that the expression of Mfn2 is reduced in tumor tissue versus in adjacent nontumorous tissues and that it negatively corresponds with tumor size and tumor prognosis." (PMID 30410558, 2018). "While some of the findings may turn out to be cell-type specific, these findings are more consistent with a role of mitofusin-2 as a MAM promoter and a tumor suppressor." (PMID 28603693, 2017). "Therefore, similar to the better-characterized mitofusin-2, it is expected that PACS-2 acts as a tumor suppressor, whose absence would be indeed expected to lead to ER–mitochondria uncoupling, but this has not been determined at this point." (PMID 28603693, 2017). "MFN2 mRNA expression in tumor and adjacent non-tumor tissues from 115 patients with HCC was investigated using quantitative real-time PCR." (PMID 27389277, 2016). "In CRC, miR-17-5p directly binds to the 3’ untranslated region of Mitofusin 2 (MFN2), leading to abnormal mitochondrial dynamics through inhibition of mitochondrial fusion, enhancement of mitochondrial fission and autophagy, and thus promoting chemoresistance in tumor cells." (PMID 39763669, 2024). "Importantly, the miR-125a/Mfn2 axis was found to be regulated by hypoxia-inducible factor 1 (HIF1); accordingly, hypoxic conditions further repressed miR-125a levels, resulting in the reduction in mitochondrial fission and increasing tumor progression." (PMID 36827549, 2023). "Indeed, in tumor cells, it has been reported that PKM2 could translocate to mitochondria and interact with MFN2 to promote mitochondrial fusion and energy production." (PMID 38062516, 2023). "The overexpression of MFN2 could rescue sor-induced cardiomyocyte necroptosis without disturbing the anti-tumor effects." (PMID 35154486, 2022). "In addition, in our study, we did not identify a correlation between Mfn2 expression and clinical pathological parameters such as tumor size and TNM stage." (PMID 35582383, 2021). "Therefore, we investigated MFN2 mRNA expression in tumor and adjacent non-tumor tissues from 115 patients with HCC and statistically evaluated the association of MFN2 mRNA expression with clinical and pathological parameters." (PMID 27389277, 2016). "Moreover, the overexpression of MFN2 could rescue sor-induced cardiomyocyte necroptosis but did not disturb its anti-tumor effects." (PMID 35154486, 2022). "The results show no significant statistical difference in gender, age, tumor size, or TNM stage between the high Mfn2 expression group and the low Mfn2 expression group." (PMID 35582383, 2021). "EGb significantly increased mRNA expression of genes related to mitochondrial functions including Mitofusin-2 (Mfn2) and dynamin related protein-1 (Drp1) in Normal group when compared to the PBS control group (p < 0.05), but there were no significant changes observed in the Tumor group." (PMID 29197355, 2017).
peripheral neuropathy (32 papers, 2006 to 2026). A disorder affecting the peripheral nervous system. "MFN2 was the second most frequent causative gene among 1211 genetically diagnosed inherited peripheral neuropathy cases in Japan." (PMID 41030121, 2026). "Pathogenic variants in the mitochondrial protein MFN2 are typically associated with a peripheral neuropathy phenotype, but can also cause a variety of additional pathologies including myopathy." (PMID 40175090, 2025). "In a large cohort study, a patient with early-onset peripheral neuropathy was reported who was compound heterozygous for Q367H and P184R MFN2 variants." (PMID 40175090, 2025). "Charcot–Marie–Tooth disease type 2 A (CMT2A) disease is a peripheral neuropathy resulting from mutations in the mitochondrial fusion protein mitofusin-2 (MFN2), a large GTPase implicated in mitochondrial fusion and tethering with the endoplasmic reticulum." (PMID 38652325, 2024). "We surmise that the combination of mitophagy and fusion defects evokes cardiac disease, whereas combined mitochondrial motility and fusion defects described for many CMT2A-linked MFN2 mutations (including those studied herein) provoke peripheral neuropathy." (PMID 37910431, 2023). "In humans, over 100 MFN2 mutations are associated with a form of inherited peripheral neuropathy, Charcot–Marie–Tooth disease type 2A (CMT2A)." (PMID 37508383, 2023). "While it is difficult to separate the many functions of MERCs and MFN2, as there is considerable overlap, we suggest that MERC dysfunction plays a significant role in the peripheral neuropathy pathology caused by CMT2A MFN2 variants." (PMID 35399520, 2022). "Exemplifying the importance of MFN2, pathogenic variants in MFN2 are established to cause the peripheral neuropathy Charcot-Marie-Tooth Disease Subtype 2A (CMT2A)." (PMID 35399520, 2022). "Given the well-defined role of MFN2 in mediating mitochondrial fusion, it is often assumed that impaired fusion is the primary cause of peripheral neuropathy." (PMID 33810506, 2021). "Over 100 mutations in MFN2 have been reported to be associated with peripheral neuropathy, including examples of both autosomal dominant and recessive inheritance (including semi-dominant inheritance)." (PMID 33810506, 2021). "MFN2 was one of the first mitochondrial dynamics proteins linked to peripheral neuropathy, with pathogenic variants being the leading cause of autosomally inherited axonal CMT." (PMID 33810506, 2021). "For example, mitofusin-2 is necessary for cerebellar development in mice, and dominant negative variants of mitofusin-2 are associated with Charcot–Marie–Tooth disease type 2A, a length dependent peripheral neuropathy in man." (PMID 33488670, 2020). "Charcot–Marie–Tooth disease (CMT) type 2A is a form of peripheral neuropathy, due almost exclusively to dominant mutations in the nuclear gene encoding the mitochondrial protein mitofusin-2 (MFN2)." (PMID 30649465, 2019). "As a result of panel testing a single family was diagnosed with a peripheral neuropathy due to a MFN2 mutation." (PMID 28877744, 2017). "Although there are several hints linking peripheral neuropathies to the mitochondrial network, the function of mitofusins in peripheral nerves and also the role of MFN2 mutations in the pathogenesis of peripheral neuropathy is only partly understood." (PMID 16762064, 2006). "Thus, we characterize a novel MFN2 variant in a patient with an atypical presentation that separates peripheral neuropathy and myopathy phenotypes, and establish a potential pathomechanism connecting MFN2 dysfunction to mtDNA-mediated inflammation." (PMID 40175090, 2025). "In addition to peripheral neuropathy, patients with certain MFN2 variants can present with other pathogenic phenotypes, such as myopathy, optic atrophy, sensorineural hearing loss, ataxia, or multiple symmetric lipomatosis." (PMID 40175090, 2025).
peripheral neuropathy (continued). "Moreover, MFN2 dysfunction can lead to disease as mutations in MFN2 cause the peripheral neuropathy Charcot-Marie-Tooth Disease Type 2A (CMT2A)." (PMID 35399520, 2022). "However, other types of cellular dysfunction that are also linked to MFN2 dysfunction, such as altered lipid droplets and impaired MERCs, can also cause peripheral neuropathy." (PMID 35399520, 2022). "Furthermore, MFN2 mutations can be associated with complex phenotypes in addition to peripheral neuropathy, which occur more commonly with recessive mutations." (PMID 33810506, 2021). "However, despite the general assumption that impaired mitochondrial fusion causes the peripheral neuropathy phenotype, only a few pathogenic MFN2 variants have been investigated for their effects on MFN2 functions." (PMID 38274408, 2021). "Mt-ER contacts, which are impacted by variants in several peripheral neuropathy proteins (e.g., MFN2, GDAP1, ATL3), are important for mediating mitochondrial function, but are also important for mitochondria fission, motility, and likely by extension quality control." (PMID 33810506, 2021). "Notably, several pathogenic MFN2 associated with peripheral neuropathy variants (e.g., V69F, L76P, R94Q, P251A, R280H, W740S) have been demonstrated to impair mitochondrial transport." (PMID 33810506, 2021). "Since cisplatin-induced peripheral neuropathy is linked to mitochondrial damage and alterations in their transport, it is possible that a reduction in Mfn2 expression could lead to impairment of mitochondria axonal transport." (PMID 31075828, 2019). "Mutations in MFN2 cause Charcot Marie Tooth Type 2A, a peripheral neuropathy." (PMID 28380071, 2017). "With respect to some of the other functions performed by MFN2, such as lipid metabolism and mitophagy, we do not yet have a broad enough understanding of how they are impacted by different MFN2 variants to know whether they underlie the peripheral neuropathy seen in CMT2A." (PMID 35399520, 2022). "Calpain can also degrade mitofusin 2 (MFN2), a crucial mitochondrial outer membrane fusion regulator, and MFN2 mutations cause length-dependent, peripheral neuropathy (OMIM: 608507)." (PMID 38891774, 2024). "Meanwhile, specific pathogenic variants in a number of essential fusion (OPA1 and MFN2) and fission (DRP1) proteins lead to various neuronal pathologies in humans, such as optic atrophy, peripheral neuropathy, and encephalopathy." (PMID 33810506, 2021). "Here, we focus specifically on MFN2 and OPA1, as pathogenic variants in these genes are clearly related to a peripheral neuropathy phenotype." (PMID 33810506, 2021). "Similar to fusion, the variable mtDNA phenotypes linked to certain MFN2 variants suggest that mtDNA impairments are not necessarily linked to the peripheral neuropathy phenotype in CMT2A patients." (PMID 35399520, 2022). "Further, a study inDrosophila indicated that MFN2 could regulate ER stress, and peripheral neuropathy in diabetic patients is also thought to be partly due to ER stress." (PMID 38274408, 2021). "HMSN has a prevalence of 1 in 2500, with more than 80 genes recognized to cause peripheral neuropathy, although approximately 90% of all cases are attributable to lesions in only four genes (PMP22, MFN2, MPZ and GJB1) and the majority of diseases have autosomal dominant inheritance." (PMID 33810506, 2021). "Finally, similar to the patient we describe here, a novel ENU-induced Mfn2 mouse model characterized L643P as a variant that causes muscle myopathy without peripheral neuropathy." (PMID 40175090, 2025). "Interestingly, mutations in MFN2 but not MFN1 are causative of the peripheral neuropathy Charcot–Marie–Tooth type 2A, in line with an additional function of MFN2 for neuronal homeostasis." (PMID 37627263, 2023). "As pathogenic variants in MFN2 are typically associated with the peripheral neuropathy CMT2A, it was not clear whether the D414V variant is responsible for these patient phenotypes." (PMID 38274408, 2021).
peripheral neuropathy (continued). "Mutations in MFN2 are causal for Charcot-Marie-Tooth disease type 2A (CMT2A), an inherited peripheral neuropathy for which no curative treatment currently exists." (PMID 40612231, 2025). "Treatments of peripheral neuropathies might consequently involve genetic approaches to introduce wild type MFNs and GDAP1, as shown recently in a MFN2 transgenic mouse model, or pharmacological approaches to target these proteins." (PMID 34295920, 2021). "Thus, the mechanism linking MFN2 dysfunction to peripheral neuropathy is likely not solely due to reduced fusion." (PMID 33810506, 2021). "However, one ongoing problem in disease-related MFN2 research is the lack of a knock-in mouse that accurately models the genetics AND the severe, early-onset peripheral neuropathy phenotypes commonly seen in patients with CMT2A, despite a great deal of effort to produce such mouse models." (PMID 37508383, 2023).